WNK2 (WNK lysine deficient protein kinase 2)
Description:
Serine/threonine-protein kinase component of the WNK2-SPAK/OSR1 kinase cascade, which plays an important role in the regulation of electrolyte homeostasis, cell signaling, survival, and proliferation. The WNK2-SPAK/OSR1 kinase cascade is composed of WNK2, which mediates phosphorylation and activation of downstream kinases OXSR1/OSR1 and STK39/SPAK (By similarity). Following activation, OXSR1/OSR1 and STK39/SPAK catalyze phosphorylation of ion cotransporters, regulating their activity (By similarity). Acts as an activator and inhibitor of sodium-coupled chloride cotransporters and potassium-coupled chloride cotransporters respectively. Activates SLC12A2, SCNN1A, SCNN1B, SCNN1D and SGK1 and inhibits SLC12A5. Negatively regulates the EGF-induced activation of the ERK/MAPK-pathway and the downstream cell cycle progression. Affects MAPK3/MAPK1 activity by modulating the activity of MAP2K1 and this modulation depends on phosphorylation of MAP2K1 by PAK1. WNK2 acts by interfering with the activity of PAK1 by controlling the balance of the activity of upstream regulators of PAK1 activity, RHOA and RAC1, which display reciprocal activity.
Synonyms: KIAA1760; PRKWNK2; SDCCAG43; P/OKcl.13; NY-CO-43
Tractability: Small molecule: a high-quality ligand is known; it belongs to a druggable protein family. Antibody: UniProt places it where antibodies can reach, with high confidence; its Gene Ontology location is reachable by antibodies, with medium confidence. PROTAC: ubiquitination databases record sites on it; its protein half-life has been measured; a small molecule that binds it is known.
Target class: Kinase; Enzyme; Protein Kinase; Other protein kinase Wnk family; Other protein kinase group
Gene: Protein-coding gene on chromosome 9 (93,184,122 to 93,320,572, forward strand). Ensembl gene ENSG00000165238.
Subcellular location: Cytoplasm; Cell membrane
Subcellular location (Human Protein Atlas): Cytosol
Pathways (Reactome):
Transport of small molecules: Stimuli-sensing channels
Gene Ontology:
Molecular function: protein binding; ATP binding; protein serine kinase activity; protein serine/threonine kinase activity; protein kinase activity
Biological process: monoatomic ion homeostasis; negative regulation of cell population proliferation; negative regulation of ERK1 and ERK2 cascade; positive regulation of canonical Wnt signaling pathway; positive regulation of sodium ion transmembrane transporter activity; protein autophosphorylation; protein phosphorylation; DNA damage response; intracellular signal transduction; regulation of monoatomic cation transmembrane transport; homeostatic process; negative regulation of intracellular signal transduction
Cellular component: cytoplasm; plasma membrane; cytosol
Genetic constraint (gnomAD): Loss-of-function variants: 65 observed, 157.24 expected, observed/expected ratio (o/e) 0.41, 90% interval 0.34 to 0.51. The upper end of that interval is the gene's LOEUF score, 0.51, which puts it in group 2 of 6, group 1 being the genes least tolerant of losing a copy. Missense variants: 2,641 observed, 2,756.3 expected, observed/expected ratio (o/e) 0.96, 90% interval 0.93 to 0.99. Synonymous variants: 1,413 observed, 1,238 expected, observed/expected ratio (o/e) 1.14, 90% interval 1.09 to 1.19.
Homologues: Orthologues: macaque WNK2 (95% identical), chimpanzee WNK2 (93% identical), mouse Wnk2 (79% identical), rat Wnk2 (79% identical), dog WNK2 (78% identical), pig WNK2 (77% identical), guinea pig WNK2 (74% identical), tropical clawed frog wnk2 (48% identical), zebrafish wnk2 (37% identical), Drosophila melanogaster Wnk (22% identical), Caenorhabditis elegans wnk-1 (21% identical). Paralogues in human: WNK1 (31% identical), WNK3 (27% identical), WNK4 (21% identical), DSTYK (7% identical), NRBP1 (7% identical), NRBP2 (7% identical).
Diseases named in the same sentence as WNK2 in open-access papers:
WNK2 is named in the same sentence as 43 diseases in open-access papers, as found by Europe PMC text mining. Sharing a sentence is not in itself a finding about the gene and the disease. The quoted sentences say what the papers report.
meningioma (6 papers, 2018 to 2024). A generally slow growing tumor attached to the dura mater. "With further study, they found that dense aberrant methylation was associated with decreased WNK2 expression in these meningiomas and that aberrant DNA methylation existed in approximately 60 CpGs in the 3′ part of the island, with very little methylation in the 5′ region." (PMID 33014773, 2020). "Indeed, increasing tumor grade is associated with increased expression of VEGF, Ki67, TOP2, PD-1, and PDGFRB, while hypermethylation of RIZ1 and WNK2 leads to loss of protein expression in high grade meningioma." (PMID 31970090, 2019). "WNK2 was recently discovered to be epigenetically silenced through promoter hypermethylation in gliomas and meningioma, suggesting its role as a growth suppressor." (PMID 33428330, 2021). "Finally, our findings with respect to the hypermethylation of the tumor suppressor and familial meningioma WNK2 in grade 2 and 3 meningioma are consistent with previously published data, which suggested epigenetic alterations to be the dominant, grade-specific mechanism of gene inactivation." (PMID 36551712, 2022).
breast carcinoma (5 papers, 2020 to 2023). "When miR-370 was suppressed in breast cancer xenografts, there was an elevation in WNK2 expression, leading to a reduction in cell proliferation and tumor formation." (PMID 37627077, 2023). "Further, an increased level of MicroRNA 370 (miR-370) plays a role in controlling the activity of the WNK2 gene in breast cancer." (PMID 37627077, 2023). "WNK2 functions as an oncogene, and the decreased activity of this kinase is important in metastasis in breast cancer, glioblastoma, and lung cancer." (PMID 37627077, 2023). "For instance, miRNA-370 promotes breast cancer development by suppressing WNK2, and LINC00858 enhances gastric cancer proliferation by reducing WNK2 promoter methylation." (PMID 35549643, 2022). "Meanwhile, breast cancer studies have identified WNK2 as a downstream target of MiR-370, which mainly exerts its oncogenic function through down-regulation of the tumor suppressor WNK2, thereby affecting cell proliferation and tumor growth." (PMID 35743814, 2022). "In the context of breast cancer, the overexpression of CBX8 has been found to suppress WNK2." (PMID 37627077, 2023).
glioma (5 papers, 2015 to 2023). A benign or malignant brain and spinal cord tumor that arises from glial cells (astrocytes, oligodendrocytes, ependymal cells). "We further demonstrate that downregulation of MMP2 by WNK2 is associated with decreased levels of glioma cell invasion." (PMID 25596741, 2015). "Thus, WNK2 promoter methylation and silencing in gliomas is associated with increased JNK activation and MMP2 expression and activity, thus explaining in part tumor cell invasion potential." (PMID 25596741, 2015). "A172 WNK2 cells presented a significant decrease in LC3B and p62 protein levels, and in LC3A/B ratio when compared with control cells, after treatment with baf A1 + everolimus, suggesting that WNK2 overexpression inhibits the autophagic flux in gliomas." (PMID 32093151, 2020). "WNK2 is a tumor suppressor gene expressed in normal brain, and silenced by promoter methylation in gliomas." (PMID 25596741, 2015). "The understanding of the cellular alterations associated with WNK2 downregulation are of great importance given the fact that a high percentage of gliomas present WNK2 promoter methylation, compared with normal brain tissue." (PMID 25596741, 2015). "In tumors, WNK2 expression was found downregulated by promoter hypermethylation both in human gliomas as in other tumor types." (PMID 25596741, 2015). "A high percentage of WNK2 promoter methylation in gliomas was reported by our and other groups, and consequent decrease in the enzyme protein expression was associated with increased levels of glioma cell invasion." (PMID 25596741, 2015). "In gliomas, our group recently reported that WNK2 downregulation results in increased cell proliferation, tumor growth, cell migration and invasion, corroborating other's theory that WNK2 functions as a tumor-suppressor gene." (PMID 25596741, 2015). "Since the number of GBMs with high WNK2 expression is very limited (only 4 of 248 cases with log2 median-intensity value > 0), we grouped high and low-grade gliomas in order to assess the correlation of WNK2 levels with MMPs and IL6 expression." (PMID 25596741, 2015). "The results obtained after performing matrigel invasion assays indicate that MMP2 is necessary for glioma cell invasion, and that the WNK2 presence is sufficient to suppress the invasive phenotype." (PMID 25596741, 2015). "However, in glioma cell lines A172 and human leukemia cell lines K562, WNK2 is found to markedly downregulate the expression of LC3B and p62 and inhibit autophagy." (PMID 36123332, 2022). "Therefore, the present study aimed to explore the in vitro role of WNK2 in autophagic process in gliomas." (PMID 32093151, 2020). "Patients without WNK2 exhibited poor prognosis, and its downregulation was associated with increased glioma cell invasion." (PMID 25596741, 2015). "In this line, our results point to the fact that either WNK2 re-expression or JNK inhibition may improve therapeutic modalities in the treatment of gliomas." (PMID 25596741, 2015). "Our group previously showed that Rac1 is upregulated following WNK2 silencing in gliomas." (PMID 25596741, 2015). "These in vitro findings may contribute to our understanding of the mechanisms that lead to glioma cell invasion in cases where WNK2 is silenced by promoter hypermethylation, and provide a novel therapeutic strategy in glioma treatment." (PMID 25596741, 2015). "If we assume that JNK is a general MMP2 inhibitor in gliomas, even patients with normal WNK2 expression treated with a JNK inhibitor would better benefit from the treatment, both because of the invasion inhibition, and by the enhancement of temozolomide cytotoxicity." (PMID 25596741, 2015). "One of the main MMP2 functions is ECM remodeling leading to cell invasion, namely in gliomas, and since our group has previously demonstrated that WNK2 is a negative regulator of glioma cell invasion, it was further determined whether MMP2 is involved in invasion of WNK2-negative cells." (PMID 25596741, 2015).
glioma (continued). "In brain tumors, WNK2 methylation specifically occurs in meningiomas (5 of 6 grade II and 5 of 7 grade III cases in a study) and adult gliomas (29 of 166 cases in a study)." (PMID 36123332, 2022). "In this study, the assessment of the autophagic process using different methodological approaches has suggested that the presence of WNK2 inhibits the autophagic flux in glioma cell lines and it is independent of the mTOR pathway." (PMID 32093151, 2020). "Here we showed that MMP2 expression and activity are increased in glioma cell lines that do not express WNK2." (PMID 25596741, 2015). "Interestingly, the treatment with the MMP2 inhibitor suppressed the invasion induced by the WNK2 silencing, suggesting the existence of a WNK2-dependent MMP2 activity, which is involved in the glioma invasion." (PMID 25596741, 2015). "However, the role of WNK2 downregulation in proteolytic events related to glioma cell invasion was not explored." (PMID 25596741, 2015). "This study was performed in a rat glioma cell line in which the WNK2 methylation status was not tested, and it cannot be excluded that the downregulation of WNK2 may activate alternative signaling pathways involving JNK kinase." (PMID 25596741, 2015). "WNK2 gene, a member of the WNK (with no lysine (K)) subfamily, acts as a tumor suppressor gene in gliomas, regulating cell migration and invasion; however, its role in autophagy process is poorly explored." (PMID 32093151, 2020).
colon carcinoma (4 papers, 2020 to 2024). "LINC00858 reportedly regulates HNF4α and WNK2 to produce a tumor-promoting function in colon cancer." (PMID 35468892, 2022). "For the top colon cancer MEGs, the consistent tumor suppressor genes included MAP2K4, MAPK10, RUNX3, WNK2 (the four genes were identified by the TSGene 2.0 database), BECN1, FASN, NAT1, and NR3C2." (PMID 33273919, 2020).
glioblastoma (4 papers, 2020 to 2024). The most malignant astrocytic tumor (WHO grade IV). "In this study, assessment of the autophagic process has suggested that the presence of WNK2 inhibits the autophagic flux in glioblastoma cell line." (PMID 32093151, 2020). "In conclusion, the evaluation of the autophagic process demonstrated that WNK2 inhibits the autophagic flux in glioblastoma cell line." (PMID 32093151, 2020). "The WNK2-methylated human glioblastoma cell line A172 WT (wild type) was compared to transfected clones A172 EV (empty vector), and A172 WNK2 (WNK2 overexpression) for the evaluation of autophagy using an inhibitor (bafilomycin A1—baf A1) and an inducer (everolimus) of autophagic flux." (PMID 32093151, 2020).
hepatocellular carcinoma (3 papers, 2021 to 2023). A malignant tumor that arises from hepatocytes. "The reduced levels of the WNK2 protein, leading to an elevated risk of hepatocellular carcinoma recurrence, can be attributed to somatic mutations and copy number variations." (PMID 37627077, 2023). "WNK2 somatic mutations and copy number loss were reported in hepatocellular carcinoma, resulting in lower WNK2 protein levels, which were associated with early tumor recurrence linked to enhanced ERK1/2 signaling." (PMID 33428330, 2021). "Notably, WNK2 has been identified as a key driver associated with hepatocellular carcinoma in the Chinese population following curative resection." (PMID 37627077, 2023). "The inactivation of the WNK2 gene, known for its tumor suppressor function, resulted in the activation of the ERK1/2 signaling pathway in hepatocellular carcinoma." (PMID 37627077, 2023).
lung carcinoma (2 papers, 2022 to 2023). "Elevated levels of CBX8 have been associated with the reduced expression of WNK2 and enhanced metastasis both in vitro and in vivo across various cancer cell types, including lung cancer." (PMID 37627077, 2023).
ovarian carcinoma (2 papers, 2022 to 2026). A malignant neoplasm originating from the surface ovarian epithelium. "Hence, we demonstrate that miR-324-3p suppressed ovarian cancer progression by targeting the WNK2/RAS pathway." (PMID 35549643, 2022).
abscess (1 paper, 2025). An inflammatory process characterized by the accumulation of pus within a newly formed tissue cavity which is the result of a bacterial, fungal, or parasitic infection or the presence of a foreign body. "IGFL2 and WNK2 showed negatively correlated with abscess count (r = -0.44, p = 0.1; r = -0.43, p = 0.11)." (PMID 40455785, 2025).
anxiety disorder (1 paper, 2025). A category of psychiatric disorders which are characterized by anxious feelings or fear often accompanied by physical symptoms associated with anxiety. "WNK2 has been implicated in neurite outgrowth and differentiation, while SMIM4 has been linked to anxiety disorders, particularly in the anterior cingulate cortex." (PMID 41211100, 2025).
asthma (1 paper, 2020). "The BLAST analysis showed that MBP and WNK2 DEGs have five other similar genes in the asthma-related gene group." (PMID 32512817, 2020).
B-cell lymphoma (1 paper, 2024). "However, several associations have not yet been reported, including overexpression of WNK2 in high-grade B-cell lymphoma, of FAT4 in multiple myeloma, and of LRP1B in hairy cell leukemia (HCL), hairy cell leukemia variant (HCL-V), and marginal zone lymphoma (MZL)." (PMID 38769532, 2024).
cervical cancer (1 paper, 2022). A primary or metastatic malignant neoplasm involving the cervix. "For instance, WNK2 suppresses cervical cancer by negatively modulating the MEK1/ERK1/2 pathway." (PMID 35549643, 2022). "For example, WNK2 suppresses cervical cancer by negatively modulating the MEK1/ERK1/2 pathway." (PMID 35549643, 2022).
chordoma (1 paper, 2017). Chordomas are rare malignant tumors arising from embryonic remnants of the notochord in axial skeleton. "ULK4, NPR1 and CDKL4 were the top most expressed kinases in the Chor-IN-1 cell line, while FGFR3, KDR and WNK2 were less expressed or absent in Chor-IN-1 cells as compared to the other chordoma lines." (PMID 28835717, 2017).
clear cell renal carcinoma (1 paper, 2022). A malignant epithelial neoplasm of the kidney characterized by the presence of lipid-containing clear cells within a vascular network. "The finding that LAMA4, BIRC7, GALNTL6, WNK2, and IGFBP2 are potential targets of miR-217 at different times of tumor evolution may help to develop stage-specific strategies, taking into account the differential expression of miR-217 in each stage of clear cell renal carcinoma progression." (PMID 35936681, 2022).
heart failure (1 paper, 2022). Inability of the heart to pump blood at an adequate rate to meet tissue metabolic requirements. "Carboxylesterase 1D (CES1D), whirlin (WHRN), and WNK lysine deficient protein kinase 2 (WNK2) were the three genes with random absolute values of LogFC and indicators of heart failure (natriuretic peptide B, NPPB) detected." (PMID 35886059, 2022). "The three genes with random absolute values of LogFC and indicators of heart failure (natriuretic peptide B, NPPB) were detected: carboxylesterase 1D (CES1D), whirlin (WHRN), and WNK lysine deficient protein kinase 2 (WNK2)." (PMID 35886059, 2022).
inflammatory bowel disease (1 paper, 2025). A spectrum of small and large bowel inflammatory diseases of unknown etiology. "Studies suggest that WNK2-associated loci linked to susceptibility to inflammatory bowel disease also exhibit a significant association with pyoderma gangrenosum, both of which are comorbidities of HS." (PMID 40455785, 2025).
neuroendocrine carcinomas of (1 paper, 2023). "PIK3CA, WNK2, and KMT2B underwent mutations in both the dMMR-like subtype of NECC (50% – 75%) and in NECE (60% – 80%) specimens, while exhibiting infrequent mutational occurrences in publicly available data pertaining to neuroendocrine carcinomas of the lung or bladder (< 10%)." (PMID 37920164, 2023).
pancreatic ductal adenocarcinoma (1 paper, 2021). An infiltrating adenocarcinoma that arises from the epithelial cells of the pancreas. "WNK2 was also found to be downregulated via epigenetic silencing in early pancreatic ductal adenocarcinoma and may support cell proliferation through the Mitogen‐activated protein kinase (MAPK) signaling pathway." (PMID 33428330, 2021).
rheumatoid arthritis (1 paper, 2025). A chronic, systemic autoimmune disorder characterized by inflammation in the synovial membranes and articular surfaces. "Chondrocytes lacking WNK2 have a significant downregulation of pathways associated with OA, rheumatoid arthritis, immunogenic cell death and fibrosis, and this response is not abrogated by hyperosmotic treatment." (PMID 40592720, 2025).
serous ovarian adenocarcinoma (1 paper, 2022). "Cox regression showed that in serous ovarian adenocarcinoma, the higher the WNK2 expression, the shorter the patients’ survival time." (PMID 35549643, 2022).